SFRP4 (secreted frizzled related protein 4)
Diseases named in the same sentence as SFRP4 in open-access papers (continued):
Sharing a sentence is not in itself a finding about the gene and the disease.
atherosclerosis (6 papers, 2017 to 2025). A disease characterized by the build-up of fatty material and calcium deposition in the arterial wall resulting in partial or complete occlusion of the arterial lumen. "Based on these findings, this study aims to explore the underlying molecular mechanisms governing SFRP4 regulation of atherosclerosis." (PMID 37143778, 2023). "Correlation analysis and multivariate linear regression analysis were used to determine the association of SFRP4 expression with atherosclerosis as well as clinical risk factors." (PMID 29037197, 2017). "SFRP4 alleviates atherosclerosis in ApoE−/− mice by reducing inflammation and oxidative stress and acting via the Wnt/β-catenin signaling pathway." (PMID 40362725, 2025). "SFRP4 is a unique and pleiotropic adipokine that has a protective function against the development of atherosclerosis via several mechanisms." (PMID 37143778, 2023). "In conclusion, this study presents evidence that overexpression of SFRP4 protects against atherosclerosis." (PMID 37143778, 2023). "Animal studies suggest that SFRP4 inhibits the progression of atherosclerosis and alleviates ischemia-induced cardiomyocyte apoptosis and heart failure in ischemic cardiomyopathy." (PMID 38188253, 2023). "SFRP4 is moderately expressed in the cardiovascular system and plays an important role in atherosclerosis (AS)-related CAD." (PMID 38188253, 2023). "To verify this hypothesis, we injected Ad-SFRP4 via the tail vein and found SFRP4 overexpression attenuated atherosclerosis plaque formation but also improved the plasma lipids, which was consistent with Zhang and his collegues." (PMID 37143778, 2023). "In order to confirm this assumption, ApoE knockout (KO) mice, the most popular animal model for human atherosclerosis, were fedwith a western diet and injected with an adenovirus (Ad)-SFRP4 or an Ad-green fluorescent protein (GFP) adenovirus through the tail vein for 12 weeks." (PMID 37143778, 2023). "Importantly, in our study, we found that the expression of SFRP4 was elevated in ApoE KO mice, indicating that SFRP4 play a role in the progression of atherosclerosis." (PMID 37143778, 2023). "EAT is not separated from the myocardium or coronary artery vascular wall by fascia; thus, SFRP4 might have a direct effect on atherosclerosis through a paracrine or vasocrine pathway." (PMID 29037197, 2017). "Therefore, circulating overexpression of SFRP4 may offer a potential effective for preventing atherosclerosis." (PMID 37143778, 2023). "Additionally, the levels of SFRP4 in control group are significantly lower than those in T2DM, CHD and T2D+CHD, indicating that SFRP4 may be a predictive marker for atherosclerosis particularly in diabetic patients." (PMID 34489867, 2021). "However, the exact role of SFRP4 in CAD and atherosclerosis remains unknown and should be investigated in prospective studies." (PMID 29037197, 2017).
cervical cancer (6 papers, 2012 to 2025). A primary or metastatic malignant neoplasm involving the cervix. "MicroRNA-96-5p facilitated the viability, migration, and invasion of cervical cancer cells by silencing SFRP4." (PMID 38993819, 2024). "For example, genes like APOD, ACKR1, and SFRP4 have been recognized as significant in cervical cancer, and our analysis supports their involvement in tumor progression and patient survival, thereby reinforcing their potential as biomarkers in clinical practice." (PMID 40678068, 2025). "On the contrary, miR-96-5p was overexpressed in cervical cancer, which could promote cancer cell proliferation and metastasis via SFRP4." (PMID 33715625, 2021). "By integrated bioinformatics analysis of cervical cancer datasets from the Gene Expression Omnibus (GEO), DPP4 and SFRP4 were identified among the 8 top downregulated hypermethylated tumor suppressor genes." (PMID 32899940, 2020).
endometrial cancer (6 papers, 2011 to 2022). Primary or metastatic malignant neoplasm involving the endometrium (mucous membrane that lines the endometrial cavity). "A previous study demonstrated that sFRP4 bound to Wnt7a and inhibited canonical Wnt7a signaling in human endometrial cancer cells." (PMID 25170755, 2014). "A relationship between down-regulation of SFRP1 and SFRP4 and microsatellite instability is known for endometrial cancers." (PMID 22363760, 2012). "In addition, SFRP4 expression is also reduced in endometrial carcinomas and sarcomas confirming an important role in normal endometrial function." (PMID 21858178, 2011). "On the other hand, HAND2-AS1, PEG3, OGN, SFRP4, WT1, FOXL2 and EFEMP1 were significantly lower in endometrial cancer tissues than in normal tissues." (PMID 32555395, 2020). "SFRP4 also suppresses, depending on the receptor, Wnt-7a-induced proliferation via canonical and non-canonical pathways in endometrial cancer cell lines." (PMID 22363760, 2012).
glioblastoma (6 papers, 2017 to 2024). The most malignant astrocytic tumor (WHO grade IV). "DNA promoter methylation of SFRP4 was exclusively observed in diffuse astrocytoma (8/11 cases, 72.7%), while all anaplastic astrocytomas and glioblastomas samples were unmethylated." (PMID 38993819, 2024). "The results of present investigation show reduced expression of SFRP4 in glioblastomas compared to lower grade diffuse gliomas, indicating its tumor suppressor character." (PMID 38993819, 2024). "sFRP4 expression was then investigated in iPSC, iPSC-GBM, iPSC-GSCs, iPSC-derived sFRP4 overexpressed glioblastoma cells and was found to be upregulated only in iPSC-derived sFRP4 overexpressed glioblastoma cells as confirmed by qPCR." (PMID 37509281, 2023). "In previous studies, our group has shown that sFRP4 has an anti-proliferative capacity in CSCs derived from breast, prostate, ovary, glioblastoma multiforme, and head and neck tumours." (PMID 29385093, 2018). "Furthermore, it has been reported that the SFRP4 reduces the stemness of glioblastoma by its netrin-like domain." (PMID 38993819, 2024). "A significant connection between the age of tumor occurrence and the methylation of SFRP4 gene promoters (p = 0.011) could also be influenced by the fact that in diffuse astrocytomas the age of onset is earlier than for glioblastomas." (PMID 38993819, 2024). "Although our study did not examine alternative mechanisms of SFRP4 silencing our search through the public databases revealed four missense mutations found in glioblastoma and one in anaplastic astrocytoma." (PMID 38993819, 2024). "In addition, LEF1, β-catenin and Wnt3a as well as CD133 were found to be downregulated in iPSC-derived sFRP4 overexpressed glioblastoma cells compared to iPSC-GSCs." (PMID 37509281, 2023). "Furthermore, we compared iPSC-GBM with iPSC-derived sFRP4 overexpressed glioblastoma cells and found MGMT expression was downregulated in iPSC-derived sFRP4 overexpressed glioblastoma cells." (PMID 37509281, 2023). "Furthermore, it has been reported that the Wnt antagonist secreted frizzled-related protein 4 (sFRP4) reduces the stemness of glioblastoma by its netrin-like domain." (PMID 37509281, 2023). "Therefore, we investigated if sFRP4 overexpression reverses the conversion of iPSC into glioblastoma cells." (PMID 37509281, 2023). "Reduced expression of SFRP4 in glioblastomas, not following promoter methylation pattern, suggests another mechanism, possible global methylation, that turns off SFRP4 expression in higher grades." (PMID 38993819, 2024). "Low SFRP4 expression predominated in higher astrocytoma grades (3 and 4) (p = 0.002) where 60% of grade 3 astrocytomas and 86.7% of glioblastomas showed weak or lack of expression." (PMID 38993819, 2024).
lung fibrosis (6 papers, 2021 to 2025). "SFRP4 has also been associated with both skin and lung fibrosis, where it has been suggested to be a potential biomarker for SSc." (PMID 37372943, 2023). "Although there are few descriptions of the association between SFRP4 and aging, it has been noted that SFRP4 expression is increased in scleroderma, correlates with skin and lung fibrosis, and may serve as a biomarker for epithelial mesenchymal transition." (PMID 36084952, 2022). "Altogether, we believe that the data we show here strongly warrant further studies to determine the role of SFRP4 in the pathology of skin and lung fibrosis." (PMID 34945116, 2021). "Several of these genes (PELI1, MAP3K8, LAMA3, EMP2, CTNNAL1, CAV1, LRRK2, SFRP4) may also be involved in lung fibrosis, a severe complication of COVID-19." (PMID 37561814, 2023). "Furthermore, the secreted frizzled receptor protein 4 (SFRP4), a protein recently associated with EMT development, has been shown to be increased in the epidermis of SSc patients, and its serum concentration appeared to correlate with the degree of skin and lung fibrosis." (PMID 40308583, 2025).
mesothelioma (6 papers, 2009 to 2024). A usually malignant and aggressive neoplasm of the mesothelium which is often associated with exposure to asbestos. "Interestingly, in β-catenin-deficient human mesothelioma cell lines, SFRP4 can still inhibit cell growth and promote apoptosis." (PMID 19586554, 2009). "Several different studies reported hypermethylation of the SFRP4 gene promoter and decreased expression of the SFRP4 protein in tumors of the endometrium, cervix, bladder, pancreas, kidney, esophagus, pituitary gland, and mesothelioma." (PMID 38993819, 2024). "However, the methylation and downregulation of SFRP4 were less common than SFRP1, 2 and 5 genes in colorectal tumor, though they were both high in mesothelioma and esophageal adenocarcinoma." (PMID 38993819, 2024).
osteoporosis (6 papers, 2014 to 2023). A condition of reduced bone mass, with decreased cortical thickness and a decrease in the number and size of the trabeculae of cancellous bone (but normal chemical composition), resulting in increased fracture incidence. "SFRP4 (secreted frizzled-related protein 4) is involved in bone mineral density, which is related to osteoporosis." (PMID 36360315, 2022). "The comprehensive understanding of the SFRP4-mediated bone developmental process could contribute to future therapeutic approaches of the diseases associated with either reduced or increased bone mineral density, facilitating, for instance, treatment of osteoporosis and osteopetrosis." (PMID 33193738, 2020).
Dupuytren’s disease (5 papers, 2016 to 2023). "Other potential causal genes at associated loci included MMP14, a missense variant previously finemapped for Dupuytren’s disease, and SFRP4." (PMID 34111113, 2021).
myocardial infarction (5 papers, 2014 to 2024). Gross necrosis of the myocardium, as a result of interruption of the blood supply to the area, as in coronary thrombosis. "In myocardial infarct-related studies, inhibition of the Wnt pathway using sFRP1, sFRP2, or sFRP4 was shown to reduce fibrosis and improve cardiac function." (PMID 37609444, 2023). "Second, circulating SFRP4 levels should be measured in a future study in which patients with different clinical types of CAD, including stable angina, unstable angina and myocardial infarction, as well as healthy controls, are enrolled." (PMID 29037197, 2017).
myocardial ischemia (5 papers, 2021 to 2026). A disorder of cardiac function caused by insufficient blood flow to the muscle tissue of the heart. "Moreover, knockdown of SFRP4 attenuates apoptosis to protect against myocardial ischemia/reperfusion injury." (PMID 37143778, 2023). "SFRP4 may pose potential implications on diabetic myocardial ischemia-reperfusion." (PMID 35290144, 2022).
psoriasis (5 papers, 2017 to 2022). An autoimmune condition characterized by red, well-delineated plaques with silvery scales that are usually on the extensor surfaces and scalp. "SFRP4 was decreased in the skin epidermis of psoriatic patients and mouse models of psoriasis by an epigenetic regulation- DNA methylation." (PMID 35075118, 2022). "Administration of SFRP4 or pharmacological inhibition of Wnt alleviated psoriasis-like dermatitis induced by IMQ." (PMID 35075118, 2022). "Several studies have previously proved the association between candidate genes involved in metabolic pathways of acitretin and the pathogenic mechanism of psoriasis, such as CSMD1, CCHCR1, GLI1, SFRP4 etc.." (PMID 28146080, 2017). "Recently, it has been shown that the expression of SFRP4 was diminished in the lesional skin of patients with psoriasis." (PMID 28146080, 2017). "The four genetic variants—rs1802073 G>T in SFRP4, rs1105223T>C in CRB2, rs3821414T>C in ARHGEF3, rs11086065A>G in ANKLE1—could be validated as predictive markers for the response to acitretin in psoriasis." (PMID 28146080, 2017).
dysplasia (4 papers, 2019 to 2026). A usually neoplastic transformation of the cell, associated with altered architectural tissue patterns. "The ENDCAP-C trial, a multicenter study to assess the role of molecular markers in improving the detection of dysplasia, identified the methylation of a five-marker panel (SFRP2, SFRP4, WIF1, APC1A, APC2) that accurately detected ulcerative colitis associated dysplasia." (PMID 41562706, 2026). "For neoplastic mucosa a five marker panel (SFRP2, SFRP4, WIF1, APC1A, APC2) was accurate in detecting pre-cancerous and invasive neoplasia (AUC = 0.83; 95% CI: 0.79, 0.88), and dysplasia (AUC = 0.88; (0.84, 0.91)." (PMID 30473377, 2019).
gestational diabetes (4 papers, 2020 to 2024). Carbohydrate intolerance first diagnosed during pregnancy. "Elevated SFRP4 levels are observed in metabolic disorders linked to IR, like T2DM and gestational diabetes mellitus (GDM)." (PMID 39911236, 2024). "Logarithmic transformed mean concentrations and standard deviation (SD) and logistic regression analysis of sFRP4, Chemerin, Leptin and Adiponectin concentrations in gestational diabetes (GDM) and uncomplicated (control) pregnancies." (PMID 33206702, 2020). "The aim of this study was to evaluate whether soluble frizzled-related protein 4 (sFRP4) concentration in the first trimester of pregnancy is individually, or in combination with Leptin, Chemerin and/or Adiponectin, associated with the development of gestational diabetes (GDM)." (PMID 33206702, 2020).
heart failure (4 papers, 2020 to 2023). Inability of the heart to pump blood at an adequate rate to meet tissue metabolic requirements. "In addition, SFRP4 is associated with ischemic cardiomyopathy, a type of heart muscle disease, and has been verified as a hub gene associated with heart failure (HF)." (PMID 38077583, 2023). "SFRP4, as the other activated upstream regulator, inhibited TNNT2 and MYH7, which contributed to the development of heart failure and arrhythmia." (PMID 32423033, 2020). "Finally, five genes (FRZB, SFRP4, ETNPPL, AQP4, C1orf105) were found to be highly co-expressed in patients with heart failure and atrial fibrillation." (PMID 36295481, 2022).
lung carcinoma (4 papers, 2010 to 2023). "In addition, overexpression of miR-31 in these cells depletes several other antagonists of Wnt signaling that have potential miR-31 binding motifs, including SFRP1, SFRP4, and WIF-1, which are often silenced in human lung cancer." (PMID 38309281, 2023).
prostate tumor (4 papers, 2009 to 2024). "We demonstrate that sFRP4 has a prominent role in basal glucose uptake in CSCs derived from breast and prostate tumour cell lines." (PMID 29385093, 2018). "This study contributes previously unknown insights of SFRP4 mRNA in the prostate tumor environment that potentially can improve diagnosis and treatment." (PMID 39511287, 2024). "Both SFRP4 and CXCL14 on the other hand are inhibitors of prostate tumor growth." (PMID 19356222, 2009).
adenomyosis (3 papers, 2022 to 2025). The growth of endometrial tissue inside the muscular wall of the uterine corpus. "Further studies are also required to validate the underlying molecular mechanism between COX-2, IFITM3, SFRP4 and adenomyosis." (PMID 38239300, 2024). "COX-2, IFITM3, and SFRP4 are significantly associated with the degree of dysmenorrhea, and they may be potential molecular targets for the treatment of dysmenorrhea in patients with adenomyosis." (PMID 38239300, 2024). "We performed differential gene analysis on cluster 24 cell populations from both groups and found that the differential genes that were remarkably overexpressed in the adenomyosis pain group were SFRP4 and MMP11 (log2(FC)>2)." (PMID 36532077, 2022). "In the current investigation, we discovered a novel cluster of NKT cells, SFRP4+IGFBP5hiNKT cells, in the foci of patients with adenomyosis pain by single-cell sequencing." (PMID 36532077, 2022). "IF confirmed that SFRP4+ NKT cells were present in the lesions of patients with adenomyosis pain and produced a significant quantity of SFRP4 into the extracellular tissue space." (PMID 36532077, 2022). "Collectively, these findings propose that SFRP4+IGFBP5hi NKT cells may drive stem cell differentiation toward neurogenic lineages through IGFBP5 expression, thereby contributing to adenomyosis-associated pain." (PMID 39936948, 2025). "COX-2, IFITM3, and SFRP4 may serve as potential molecular biomarkers or therapeutic targets in dysmenorrhea in patients with early adenomyosis." (PMID 38239300, 2024). "Meanwhile, the recently found SFRP4+IGFBP5hi NKT cells may provide a novel therapeutic target for controlling adenomyosis pain." (PMID 36532077, 2022). "Overall, single-cell analyses have revealed the complex interplay of cellular and molecular mechanisms driving adenomyosis, highlighting the potential for therapeutic interventions targeting Wnt signaling, angiogenic pathways, and pain-associated stem cell markers such as IGFBP5 and SFRP4." (PMID 39936948, 2025). "In ectopic endometrium of adenomyosis, the expression levels of COX-2 were positively correlated with the expressions of WBP2, IFITM3, and SFRP4 (r = 0.536, P < 0.01; r = 0.591, P < 0.01; r = 0.533, P < 0.01)." (PMID 38239300, 2024). "Collectively, these findings suggest that SFRP4+IGFBP5hi NKT cells were capable of converting part of the stem cells into neurogenic cells and inducing adenomyosis pain." (PMID 36532077, 2022). "We found a specific population of secreted frizzled-related protein 4 (SFRP4)+NKT cells and a large amount of undifferentiated multipotent stem cells in the adenomyosis pain group." (PMID 36532077, 2022). "WBP2 and SFRP4 were significantly expressed in the cytoplasm and cytosol of glandular cells in the ectopic endometrium of adenomyosis, but not in the myometrium and the mesenchymal cells of ectopic endometrium." (PMID 38239300, 2024). "COX-2, IFITM3, SFRP4, and WBP2 may be involved in the pathogenesis of adenomyosis." (PMID 38239300, 2024). "Thus, the expression of COX-2, WBP2, IFITM3, and SFRP4 did not correlate significantly with menstrual flow and volume in adenomyosis." (PMID 38239300, 2024). "However, in the present experiment, although we confirmed the presence of a large number of undifferentiated cells in the adenomyosis pain group, there was no further evidence on the biological functions of SFRP4 and IGFBP5." (PMID 36532077, 2022).
head and neck cancer (3 papers, 2017 to 2022). A primary or metastatic malignant neoplasm affecting the head and neck. "SFRP4 could inhibit cancer stem-like cells (CSCs) from head and neck cancers through self-renewal, cloning and expression; moreover, CSCs with such biomarkers were more sensitive to the chemotherapeutic drug cisplatin." (PMID 35892344, 2022).